NECTIN4 (nectin cell adhesion molecule 4)
Diseases named in the same sentence as NECTIN4 in open-access papers (continued):
Sharing a sentence is not in itself a finding about the gene and the disease.
ovarian cancer (39 papers, 2011 to 2025). A primary or metastatic malignant neoplasm involving the ovary. "There is evidence that serum Nectin-4 levels are associated with the grade and progression of ovarian cancer." (PMID 38606099, 2024). "In this study, we examined the role that Nectin-4 plays in several cellular functions that underlie ovarian cancer progression: cell adhesion, spheroid formation, migration, and proliferation." (PMID 28038455, 2017). "In ovarian cancer, serum Nectin-4 may serve as a potential diagnostic marker that helps discriminate benign gynecological diseases from malignancy in a panel with CA125." (PMID 37174031, 2023). "While Nectin-4 expression is generally low in normal tissues, it is increased in several tumor types and is associated with tumor progression in breast, urothelial, pancreatic, lung, and ovarian cancers." (PMID 36139571, 2022). "The expression of NECTIN4 is generally low in normal tissues, whereas it increases in various malignant tumors; its association with tumor progression has been reported among breast, urothelial, pancreatic, lung, and ovarian cancers." (PMID 33478111, 2021). "In addition to Nectin-4, other cell adhesion molecules, such as cadherins and claudin-4 have been implicated in spheroid formation and metastasis in ovarian cancer." (PMID 32629816, 2020). "Nectin-4 overexpression has been reported in numerous types of cancer including breast, bladder, esophageal, lung, gastric, pancreatic, and prostate, in addition to ovarian cancer; high Nectin-4 expression in some tumors was associated with disease progression or poor prognosis." (PMID 40075748, 2025). "In previous studies, we showed that Nectin-4 was involved in the aggregation of ovarian cancer cells and their subsequent formation into spheroids." (PMID 40075748, 2025). "Expressed at low levels in a variety of normal tissues, NECTIN4 is tumor surface antigen that is highly expressed in subsets of breast, lung, pancreatic and ovarian cancers, and in a majority of urothelial cancers." (PMID 39969205, 2025). "This drug targets the nectin-4 protein, which is overexpressed in various tumors, including ovarian cancer." (PMID 40605011, 2025). "It remains of interest in other cancers that overexpress Nectin-4, including ovarian cancer and triple-negative breast cancer." (PMID 40075748, 2025). "The protein Nectin-4 is expressed on the surface of a variety of epithelial cancer cells, including ovarian cancer cells, and plays a role in cell–cell adhesion." (PMID 40075748, 2025). "Our previously published studies using ovarian cancer cell lines show that peptide N4-P10 blocks adhesion to the extracellular domain of Nectin-1 in vitro, as do antibodies to Nectin-4." (PMID 40075748, 2025). "NECTIN‐4 serum levels are elevated in patients with non‐small cell lung, breast and ovarian cancers." (PMID 39072867, 2024). "Another family member, nectin-4, is overexpressed in ovarian cancer tissue and plays a role in tumor cell proliferation, motility, and invasion." (PMID 40836974, 2024). "The presence of nectin‐4 as a blood-based marker for ovarian cancer cells implies that it is involved in regulating endothelial functions, such as migration, proliferation, and invasion." (PMID 40836974, 2024). "Although soluble Nectin-4 has great potential and value in the diagnosis and monitoring of ovarian cancer, it still requires large-scale prospective studies for further validation and standardization." (PMID 38606099, 2024). "Remarkably, a higher level of serum Nectin-4 was detected, especially in patients with early stage ovarian cancer, such as those with low CA125." (PMID 37174031, 2023). "Another cohort study comprising 131 patients with ovarian cancer and 100 age-matched healthy controls demonstrated that preoperative collected serum Nectin-4 levels were significantly higher in patients with ovarian cancer than in controls." (PMID 37174031, 2023).
ovarian cancer (continued). "It was shown that Nectin-4 is detectable in the serum of ovarian cancer patients and allows the distinction between benign and malignant ovarian neoplasms." (PMID 36497350, 2022). "In this study, we propose Nectin-4 as a potential biomarker for ovarian cancer that has high potential to improve the detection of ovarian cancer as part of a biomarker panel, in particular by identifying early stages of the disease." (PMID 36497350, 2022). "Overall, we are aware that Nectin-4 alone cannot be used in the diagnosis of ovarian cancer, but a combination in a biomarker panel should be aimed for." (PMID 36497350, 2022). "This underlines the diagnostic value of Nectin-4 and HB-EGF for the detection of early stages of ovarian cancer." (PMID 36497350, 2022). "The ADAM17 substrates Nectin-4 and HB-EGF appear to be promising markers for the detection of early stages of ovarian cancer and are associated with prognostically favorable parameters, such as early FIGO stage and successful tumor debulking." (PMID 36497350, 2022). "Nectin-4 has been detected in bronchial, esophageal, gastric, pancreatic, urothelial, breast and ovarian cancer." (PMID 36497350, 2022). "Ovarian cancer patients showed significantly higher concentrations of both Nectin-4 (median: OvCa patients: 137.7 pg/mL, control: 0 pg/mL, p < 0.0001) and HB-EGF (median: OvCa patients: 16.4 pg/mL, control: 9.4 pg/mL, p = 0.016) compared to the control cohort." (PMID 36497350, 2022). "In this study, Nectin-4 has been most intensively investigated as a potential blood-based tumor marker for ovarian cancer." (PMID 36497350, 2022). "Our data suggest that Nectin-4 is rather a surrogate marker for initiation and progression of early ovarian cancer than a measurement of tumor mass such as Ca-125." (PMID 36497350, 2022). "In other tumor entities like ovarian cancer in vitro studies also suggest a link between Nectin-4 and proliferation and migration, but the exact effects were partly contradictory." (PMID 36268557, 2022). "For example, in ovarian cancer cells, NECTIN4 was shown to alter cell adhesion and, although control cells formed small and compact spheroids, cells in which NECTIN4 was inhibited formed loosely aggregated spheroids." (PMID 33808400, 2021). "The peptides were initially screened at a concentration of 150 μg/mL in 96-well flat-bottom ultra-low attachment plates to identify the section(s) of Nectin-4 that are active in ovarian cancer cell aggregation and spheroid formation." (PMID 32629816, 2020). "Additional studies showed elevated levels of the cleaved Nectin-4 extracellular domain in serum and ascites fluid from ovarian cancer patients." (PMID 32629816, 2020). "In previous studies, we examined the role of Nectin-4 in the biological functions of ovarian cancer cells." (PMID 32629816, 2020). "Synthetic peptides derived from Nectin-4 were tested for their ability to alter spheroid formation in two ovarian cancer cell lines." (PMID 32629816, 2020). "These peptide studies allowed the discernment of the regions of Nectin-4 that are important for cell–cell adhesion and ovarian cancer spheroid formation." (PMID 32629816, 2020). "Previous studies suggest that the cell adhesion molecule Nectin-4 plays a key role in the formation of ovarian cancer spheroids." (PMID 32629816, 2020). "In search of new targets for which putative therapeutics have already been developed, a comprehensive analysis including various validation steps revealed new evidence for Nectin 4 as potential target for selected ovarian cancer patients." (PMID 31137558, 2019). "In human ovarian cancer cells the significance of Nectin 4 in cell-cell adhesion, proliferation, and migration has been demonstrated by over-expression and silencing experiments." (PMID 31137558, 2019). "Nevertheless, understanding the biology of Nectin-4 in ovarian cancer progression is still critical to facilitate its development as a therapeutic target." (PMID 28038455, 2017).
ovarian cancer (continued). "Subsequently, we showed that Nectin-4 RNA and protein are overexpressed in ovarian cancer tissues and cell lines compared to their normal ovarian counterparts." (PMID 28038455, 2017). "The cell adhesion molecule Nectin-4 is normally expressed in early development and is aberrantly overexpressed in some epithelial cancers, including ovarian cancer." (PMID 28038455, 2017). "We also showed that the cleaved, soluble extracellular domain of Nectin-4 (sN4) is detectable at elevated levels in the sera of ovarian cancer patients." (PMID 28038455, 2017). "In the experiments presented herein, we examined the effect that knocking down Nectin-4 expression in ovarian cancer cell lines has on the various cellular behaviors that underlie metastasis." (PMID 28038455, 2017). "The objective of this study was to determine the biological significance of Nectin-4 in the adhesion, aggregation, migration, and proliferation of ovarian cancer cells." (PMID 28038455, 2017). "We discovered the overexpression of the cell adhesion molecule Nectin-4 (PVRL4) in ovarian cancer tissues by gene microarray analysis." (PMID 28038455, 2017). "To assess the clinical relevance of the cell adhesion molecule Nectin-4 and its binding partner Nectin-1 in ovarian cancer, we examined their RNA expression in patient samples, as well as the human mesothelial cell lines LP9 and Met5a." (PMID 28038455, 2017). "The cell adhesion molecule Nectin-4 is overexpressed in epithelial cancers, including ovarian cancer." (PMID 28038455, 2017). "The human ovarian cancer cell lines CAOV3 and NIH:OVCAR5 were selected for this study in order to understand the potential function of Nectin-4 in ovarian cancer progression." (PMID 28038455, 2017). "Understanding the biology of Nectin-4 in ovarian cancer progression is critical to facilitate its development as a novel therapeutic target." (PMID 28038455, 2017). "These cell lines both express moderate levels of Nectin-4, relative to a dozen other human ovarian cancer cell lines that we had previously characterized, and thus are ideal for generating cell lines that have Nectin-4 expression knocked down." (PMID 28038455, 2017). "We have also shown that Nectin-4 and its binding partner Nectin-1 are expressed in ascites cells, primary tumors, and omental metastases from ovarian cancer patients, as well as human mesothelial cells." (PMID 28038455, 2017). "In ovarian cancer, Nectin-4 has also been reported to be increased in tumour cells and tissues, compared to normal." (PMID 24386110, 2013). "Reverse transcriptase-polymerase chain reaction (RT-PCR) and quantitative RT-PCR validated the overexpression of Nectin-4 messenger RNA in ovarian cancer compared with normal ovarian cell lines and tissues." (PMID 24386110, 2013). "Other laboratories have shown that PVRL4 (Nectin 4) is up-regulated on breast, lung, and ovarian cancer tumors and cell lines." (PMID 21901103, 2011). "Of these only human PVRL4 (Nectin 4), a tumor cell marker found on breast, lung, and ovarian carcinomas, rendered cells amenable to MV infections." (PMID 21901103, 2011). "Moreover, numerous reports confirm the existence of a correlation between high expression of nectin-4 in gastrointestinal cancers (esophageal, gastric, colorectal, pancreatic) and ovarian cancer with reduced patient survival." (PMID 40244005, 2025). "Taken together, these results suggest that the efficacy of pre-treatment with peptide N4-P10 may be at least in part dependent on the level of Nectin-4 expression on the ovarian cancer cells." (PMID 40075748, 2025). "CD46 and Nectin-4 have been reported to be highly expressed on the surface of ovarian cancer cells, and MV has displayed a remarkable antitumor effect in a mouse model of ovarian cancer." (PMID 38606099, 2024). "Similarly, soluble Nectin-4 has been detected in the serum of patients with ovarian cancer, and it can be used, with CA-125, to identify benign ovarian disease and ovarian cancer." (PMID 38606099, 2024).
ovarian cancer (continued). "Significantly elevated Nectin-4 levels were detected in the blood of patients with ovarian cancer." (PMID 36497350, 2022). "To investigate whether Ca-125 and Nectin-4 could complement each other in the diagnosis of ovarian cancer, we investigated subgroups of patients with particularly low values of Ca-125." (PMID 36497350, 2022). "In addition, they showed that Nectin-4 enables differentiation between benign gynecological diseases and ovarian cancer." (PMID 36497350, 2022). "Nectin-4 is a member of the nectin family and it is weakly expressed in normal tissues while highly expressed in various tumor cells, including urothelial, lung, breast, and ovarian cancers." (PMID 35795565, 2022). "By microarray analysis, Nectin-4 was found to be overexpressed in ovarian cancer tissues." (PMID 32629816, 2020). "So far, in ovarian cancer only little is known about Nectin 4 expression and its impact on outcome." (PMID 31137558, 2019). "Due to the link between Nectin-4 and the actin cytoskeleton, we questioned whether Nectin-4 expression could affect ovarian cancer cell migration." (PMID 28038455, 2017). "The expression of Nectin-4 on the surface of ovarian cancer tumors suggests that Nectin-4 is a valid target for therapy, and our in vitro data showed that a mAb against the IgV domain of Nectin-4 almost completely blocked ovarian cancer cell adhesion to Nectin-1." (PMID 28038455, 2017). "These experiments offer insight into how ovarian cancer cells may act in vivo and may provide a rationale for the use of agents that target Nectin-4 in clinical trials." (PMID 28038455, 2017). "Taken together, these data suggest that Nectin-4 may play a role in local ovarian cancer progression by promoting tumor proliferation, migration, and invasion into the mesothelial cell lining of the peritoneum." (PMID 28038455, 2017). "The expression of Nectin-4 was increased in ovarian cancer compared with normal ovaries." (PMID 24386110, 2013). "In this study, we used live-cell imaging to demonstrate that treatment with peptide N4-P10, a 14-amino acid sequence from the extracellular domain of Nectin-4, could inhibit spheroid formation in cell lines as well as cells that were isolated from the ascites of ovarian cancer patients." (PMID 40075748, 2025). "In this study we showed that both Nectin-4 and its binding partner Nectin-1 are expressed in ovarian cancer primary tumors, ascites cells and omental metastases from patients, as well as in human mesothelial cells, setting the stage for ovarian cancer cell adhesion in vivo." (PMID 28038455, 2017). "LPA has also been shown to promote shedding of E-cadherin, consequently disrupting cell adhesion and promoting motility a ovarian cancer cells, supporting the idea that ectodomain shedding of Nectin-4 could regulate cell migration and metastasis in ovarian cancer patients." (PMID 28038455, 2017). "The second cell line tested was the ovarian cancer cell line, CAOV3, which expresses moderate levels of Nectin-4 protein but very low levels of Nectin-1 protein." (PMID 40075748, 2025). "Nectin-4 had a higher sensitivity and specificity compared to the MUC16 standard biomarker, especially for early-stage ovarian cancer." (PMID 40836974, 2024). "Even though the EGF ligands Nectin-4, HB-EGF and AREG have been described as rational targets for blood-based detection of ovarian cancer, their application as biomarkers for early-stage ovarian cancer so far has not been shown." (PMID 36497350, 2022). "In this study, we detected elevated Nectin-4 and HB-EGF serum levels in ovarian cancer patients which correlate with prognostically favorable parameters, such as early FIGO stage and successful tumor debulking." (PMID 36497350, 2022). "Since we showed a significant increase in Nectin-4 and HB-EGF in ovarian cancer compared to the control group, these two were further investigated in this study." (PMID 36497350, 2022).
ovarian cancer (continued). "It was shown that Nectin-4, HB-EGF, and AREG are proteolytically cleaved by the metalloprotease ADAM17 and represent essential factors in the regulation of ovarian cancer." (PMID 36497350, 2022). "To gain insight into the functional activity of ADAM17, we selected Nectin-4, HB-EGF and AREG as surrogate markers for ADAM17 activity and evaluated them as potential tumor markers for ovarian cancer." (PMID 36497350, 2022). "We have previously shown that many human ovarian cancer cell lines express Nectin-4; two of these cell lines, NIH:OVCAR5 and CAOV3, express moderate levels of Nectin-4." (PMID 32629816, 2020). "In the ovarian cancer cell line NIH:OVCAR5, cells that express Nectin-4 proliferated significantly faster than cells that had Nectin-4 expression knocked down by shRNA or Nectin-4-over cells." (PMID 28038455, 2017). "In NIH:OVCAR5 cells, both parental and N4-over cells had increased amounts of E-Cadherin, β-catenin, and claudin-1, compared to the knock-down cells, suggesting Nectin-4 plays a role in EMT and ovarian cancer progression." (PMID 28038455, 2017). "Multiple phase I clinical trials (NCT03542799, NCT03932565) have reported the use of TRUCKs for recurrent ovarian cancer (MUC16ecto CAR + IL-12), Nectin4-expressing solid tumors (Nectin4/FAP CAR + IL-7 and CCL19 or IL-12), and metastatic colon cancer (EGFR CAR +IL-12)." (PMID 38727262, 2024). "The aim of this study is to investigate whether the ADAM17 substrates Nectin-4, Heparin-binding EGF-like growth factor (HB-EGF) and Amphiregulin (AREG) could function as potential tumor markers for ovarian cancer." (PMID 36497350, 2022). "Therefore, in the present study, we evaluate the ADAM17 substrates Nectin-4, HB-EGF and AREG as a potential blood-based detection method for ovarian cancer." (PMID 36497350, 2022). "The second one, cited earlier, is a phase I clinical trial (NCT03932565) using fourth-generation CAR-T cells coproducing IL-7 and CCL19/IL-2 in patients with Nectin4-positive advanced malignant solid tumors such as NSCLC, breast, bladder, pancreatic and ovarian cancer." (PMID 35211124, 2022). "Therefore, Nectin-4 and HB-EGF appear to be promising blood-based biomarkers for the diagnosis of early stages of ovarian cancer." (PMID 36497350, 2022). "L1CAM was the most up-regulated single gene, known to be a negative prognostic factor in ovarian cancer, therefore fitting to the worse outcome of patients with high Nectin 4 expressing tumors in our study." (PMID 31137558, 2019). "Notably, Nectin-4 can be detected in the early stages of ovarian cancer, even when CA-125 levels are not significantly elevated in the serum." (PMID 38606099, 2024). "Whether the expression levels of Nectin-4 in ovarian cancer patients affects survival or response to therapy is not known." (PMID 28038455, 2017). "On the other hand, Nectin-4 expression was not defined as a prognostic factor in ovarian cancer." (PMID 25888293, 2015). "Our study proposes Nectin-4 and HB-EGF as promising blood-based biomarkers for the detection of early stages of ovarian cancer patients that would not have been detected by Ca-125." (PMID 36497350, 2022).